INS (insulin)
Diseases named in the same sentence as INS in open-access papers (continued):
Sharing a sentence is not in itself a finding about the gene and the disease.
type 2 diabetes (continued). "Mounting evidence has shown the active function of PE in the insulin signaling pathway, suggesting that the increased phosphatidylcholine (PC)/PE ratio can be correlated to reduced or elevated insulin sensitivity among patients with type 2 diabetes." (PMID 39764206, 2024). "As the cases of type 2 diabetes are increasing annually, international guidelines prefer insulin analogues to human insulin because of lesser weight gain, better HbA1C control and effectivity." (PMID 38378730, 2024). "A few additional small studies and RCTs have also shown benefits of insulin pump therapy in older people with type 2 diabetes." (PMID 39138689, 2024). "UBE2E2, a gene associated with obesity and type 2 diabetes, encodes the ubiquitin-conjugating enzyme E2E2 expressed in adipose tissue, and it plays a regulatory role in insulin synthesis and secretion as well as adipocyte differentiation." (PMID 38550599, 2024). "Of the patients with Cushing’s disease and type 2 diabetes, 14 received metformin, 5 received metformin with insulin, and 1 received insulin." (PMID 38541884, 2024). "Among the participants with type 2 diabetes, all reported using oral antidiabetic medications, with one participant also undergoing combined therapy that included injectable insulin." (PMID 39845677, 2024). "Type 2 diabetes (T2D) is a chronic, progressive disorder characterized by persistent hyperglycemia resulting from inadequate insulin secretion or impaired insulin utilization." (PMID 39469399, 2024). "Type II diabetes mellitus is a metabolic disorder characterized by impaired insulin metabolism, which often leads to significant suffering for patients due to its acute complications." (PMID 38254517, 2024). "A meta-analysis of numerous studies showed that the oral consumption of magnesium supplements and the incorporation of the right foods into one’s diet can significantly enhance insulin sensitivity and metabolic control in people with type 2 diabetes." (PMID 38525719, 2024). "Type 2 diabetes (T2DM) is a chronic condition characterized by high blood sugar levels due to insulin resistance or inadequate insulin production." (PMID 39211911, 2024). "Since 2018, the Swedish National Board of Health and Welfare has recommended CGM for patients with type 2 diabetes receiving multiple daily insulin injections." (PMID 38660249, 2024). "In myotubes from donors with type 2 diabetes, insulin increased glycogen synthesis by 1.7-fold, from 1.02- to 2.5-fold (p=0.0031)." (PMID 38814443, 2024). "Postprandially, insulin suppresses hepatic glucose production, a function compromised in type 2 diabetes, which was first documented by Dame Sheila Sherlock and colleagues in 1951 using hepatic venous catheterisation." (PMID 38334817, 2024). "Among patients with diagnosis of type 2 diabetes, the proportion with any prescription fill for insulin increased with advancing DPN severity, from 12.8% among those with no DPN to 43.5% among patients with severe PDPN." (PMID 39001927, 2024). "With notable reductions in HbA1C and minimal adverse effects, weekly insulin injection presents a promising option for simplifying insulin therapy and improving patient outcomes in type 2 diabetes management." (PMID 38618372, 2024). "For instance, fiber intake is well-established for its role in improving blood glucose control and insulin sensitivity in individuals with Type II diabetes." (PMID 39734671, 2024). "This is supported by evidence showing a significant impact of olive oil on glucose homeostasis and insulin sensitivity, suggesting its promotion at both individual and population levels to mitigate the burden of type 2 diabetes." (PMID 39200546, 2024). "In a randomized cross-over design, the SGLT2 inhibitor empagliflozin (E) was compared with insulin (I) treatment titrated to the same level of glycemic control in 17 patients with type 2 diabetes, BMI of > 28 kg/m2, C-peptide > 500 pM." (PMID 38184612, 2024).
type 2 diabetes (continued). "Maternal insulin regulation can be disrupted in type 2 diabetes, leading to increased insulin levels in maternal circulation and potentially influencing its presence in breast milk." (PMID 39021603, 2024). "Several glucose-lowering mechanisms exist in type 2 diabetes, such as increased insulin secretion, glucose uptake, and α-glucosidase inhibition." (PMID 39458809, 2024). "Currently, relying on exogenous insulin (INS) is the only practical way to control blood glucose levels for patients with late-stage type 2 diabetes or type 1 diabetes." (PMID 38214820, 2024). "It is reported that the vast majority of diabetes incidents are classified as type 2 diabetes (T2D), which is characterized by the impairments of insulin secretion and insulin resistance." (PMID 39339760, 2024). "Thiazolidinediones (TZD), a class of synthetic agonists of peroxisome proliferator-activated receptor gamma (PPARγ), initially used as insulin sensitizers for the treatment of type 2 diabetes, have been shown to affect cellular metabolism." (PMID 38594745, 2024). "Our department conducted a retrospective cohort study to compare the efficacy of continuous glucose monitoring devices versus capillary blood glucose in the glycemic control of inpatient type 2 diabetes on intensive insulin therapy in a Portuguese hospital." (PMID 38476508, 2024). "Elevated cortisol levels affect blood glucose (on both liver and skeletal muscles), insulin sensitivity, and pancreatic function, linking MACS to a heightened risk of type 2 diabetes." (PMID 38808111, 2024). "Adequate levels of these nutrients contribute to maintaining stable blood sugar levels, improving insulin sensitivity, and reducing the incidence of developing type 2 diabetes." (PMID 38915027, 2024). "The degree to which vitamin D supplementation affected patients' incidence of type 2 diabetes and their insulin sensitivity differed from research to study in this systematic analysis." (PMID 39822434, 2024). "TZDs including pioglitazone and rosiglitazone are used in type 2 diabetes to improve insulin sensitivity, but their use is limited by side effects such as weight gain, edema, and potential cardiovascular risks." (PMID 39594624, 2024). "Insulin glargine (Lantus) is a long-acting human insulin analog that is used in patients in type I and type II diabetes." (PMID 38365663, 2024). "Pramlintide, an analog of the peptide amylin, is recommended alongside insulin for both type 1 and type 2 diabetes." (PMID 39620004, 2024). "Sleep disturbances and circadian rhythm disturbances impair β-cell function and insulin sensitivity, leading to impaired glucose tolerance, which severely affects glycemic level control and thus exacerbates the progression of type 2 diabetes." (PMID 38375195, 2024). "In type 2 diabetes, where insulin secretion after carbohydrate ingestion is severely impaired, amino acid and protein co-ingestion were shown to substantially increase plasma insulin responses, and can assist in acute metabolic control." (PMID 39114126, 2024). "Globally, 9 million people with type 1 diabetes and 63 million people with type 2 diabetes require insulin." (PMID 39361609, 2024). "Type 2 diabetes mellitus (T2DM) is a multi-etiological metabolic disease characterized by chronic hyperglycemia, which is caused by deficiencies in insulin secretion and/or utilization." (PMID 38178198, 2024). "Insulin induced vasodilation is diminished with metabolic syndrome, type 1 or type 2 diabetes, or obesity." (PMID 38170166, 2024). "Research on GLP-1 focuses mainly on its role in stimulating insulin secretion by activating pancreatic beta cells and the potential use of hormone analogs for the treatment of type 2 diabetes and obesity." (PMID 39408213, 2024). "In the Phase II clinical trial programme, icodec was compared with glargine U100 in both insulin-naive and insulin-experienced individuals with type 2 diabetes." (PMID 38679644, 2024).
type 2 diabetes (continued). "The MOBILE RCT found that, compared with SMBG, rtCGM resulted in a greater HbA1c reduction (MD −4 mmol/mol [–0.4 pp]), improved TIR and decreased time above range (TAR) and TBR in a type 2 diabetes population treated with basal insulin (p<0.05 for all)." (PMID 38951212, 2024). "Imidazole propionate production is detrimental to insulin signaling, leading to type II diabetes, and disrupts the brain’s cognitive functions of learning." (PMID 38108654, 2024). "Glucose and insulin responses to body size-adjusted mixed macronutrient challenges predicted the development of type 2 diabetes." (PMID 38987291, 2024). "Although type 2 diabetes (T2D) is a disease of insulin resistance, most of therapies depend on giving more insulin to patients." (PMID 38172970, 2024). "The insulin response in the glycogen synthesis assay was robust in three donors with type 2 diabetes, despite their increased HOMA-IR." (PMID 38814443, 2024). "We therefore examined the impact of 12 wk of treatment with 10 mg of empagliflozin daily on micro- and macrovascular insulin sensitivity in persons with well-controlled type 2 diabetes." (PMID 38170166, 2024). "In animals with alcohol- or insulin-induced fatty liver disease, type 2 diabetes, and obesity, upregulation of AMPK can mitigate the condition." (PMID 39408346, 2024). "In type 2 diabetes, pancreatic beta cells initially compensate for peripheral insulin resistance by adapting their function and mass to secrete more insulin and retain normoglycaemia." (PMID 38814444, 2024). "When noninsulin glucose-lowering agents fail to achieve optimal glycemic control, many individuals with type 2 diabetes resort to basal insulin treatment." (PMID 38172995, 2024). "In contrast, thiazolidinediones (TZDs), the synthetic full agonists of PPARγ with robust insulin‐sensitizing functions, have been used as first‐line drugs in the clinical treatment of type 2 diabetes." (PMID 38988496, 2024). "Small molecules MRL24 and SR1664 can block the phosphorylation of PPARγ at serine 273, selectively modulate the PPARγ transactivation to insulin‐sensitivity genes, and improve type 2 diabetes." (PMID 38988496, 2024). "As a typical example, patients with obesity and type 2 diabetes display altered adipokine profiles that lead to profound metabolic risks and changes in insulin sensitivity." (PMID 39051061, 2024). "Persistent hyperinsulinism in type 2 diabetes patients exhausts the insulin production capacity of these cells." (PMID 38257363, 2024). "In the study on FMT from a person donor with a normal BMI to an obese recipient with type 2 diabetes, it was shown that insulin sensitivity increased." (PMID 38807723, 2024). "Several studies have demonstrated the involvement of miRNAs in the onset and development of type 2 diabetes, highlighting their role in regulating cell function, insulin secretion, and insulin signaling pathways in target tissues." (PMID 38805166, 2024). "The preservation of β-cells is crucial in both type 1 and type 2 diabetes as β-cell dysfunction, reduced mass, and apoptosis are central to insufficient insulin secretion in both types." (PMID 39560873, 2024). "The ability of IF to lower HbA1c, body weight, and total daily insulin dose suggests its potential as a beneficial treatment option for individuals with type 2 diabetes who are inadequately managed and undergoing insulin therapy." (PMID 39044934, 2024). "Glycemic management in type 2 diabetes is based on factors like metformin, which lowers hepatic glucose production and improves insulin sensitivity." (PMID 39759349, 2024). "This novel research indicates that quercetin-loaded extracellular vesicles can more effectively suppress β-cell apoptosis and promote insulin secretion, thereby alleviating type 2 diabetes." (PMID 38556857, 2024).
type 2 diabetes (continued). "We conclude that insulin-resistant, maladapted intramyocellular lipid storage and turnover in patients with type 2 diabetes show reversibility after endurance training through increased contributions of the saturated intramyocellular fatty acid pools." (PMID 38750012, 2024). "The aim of this study was to determine the impact of hypoglycaemia among adults with type 1 diabetes and insulin-treated type 2 diabetes on daily functioning." (PMID 39080044, 2024). "Intensive short-term insulin therapy has been shown to induce glycemic remission in severe, newly diagnosed type 2 diabetes patients." (PMID 38969701, 2024). "These cells are critically involved in the pathophysiology of type 2 diabetes and insulin sensitivity, making them ideal models for studying the inflammatory mechanisms of IR." (PMID 39627194, 2024). "The occurrence of type 2 diabetes is attributed to reduced sensitivity of insulin-sensitive tissues towards insulin, resulting in diminished glucose uptake (GU) and subsequent hyperglycemia." (PMID 39459249, 2024). "In a meta-analysis that included four RCTs (published from 2020 to 2023), involving 1035 patients with type II diabetes mellitus, Saleem compared insulin Glargine U-100 and insulin Icodec." (PMID 39861067, 2024). "Insulin-related indicators, such as HOMA-IR, have been found in relation to insulin function in type 2 diabetes and the health of insulin-producing cells." (PMID 39759349, 2024). "In ducks, the enriched KEGG pathways included “Type II diabetes mellitus”, “Sphingolipid metabolism”, “Insulin secretion”, “Dopaminergic synapse”, “Glutamatergic synapse”, “Axon guidance”, and “Neuroactive ligand-receptor interaction”." (PMID 39195547, 2024). "Metabolic reprograming through MPC inhibition has emerged as an insulin-sensitizing strategy for treatment of type 2 diabetes and has been shown to attenuate neurodegeneration in certain Parkinson’s disease models." (PMID 39546604, 2024). "Moderate SIRT6 overexpression can increase insulin sensitivity in skeletal muscle and liver, which has a protective effect against diet-induced type II diabetes mellitus." (PMID 39372420, 2024). "Fasting levels of insulin were expectedly elevated in the type 2 diabetes group compared to the control group." (PMID 38276866, 2024). "In conclusion, this study provides novel insights into the subjective daily functioning of adults with type 1 diabetes and insulin-treated type 2 diabetes following daytime and night-time hypoglycaemia episodes." (PMID 39080044, 2024). "In mice, Adcy3 deficiency leads to impaired insulin sensitivity and dyslipidemia, and studies in humans have found that loss-of-function variants in ADCY3 increase the risk for obesity and type 2 diabetes." (PMID 39329159, 2024). "For example, in different types of transgenic animal models of type II diabetes, Akt2 −/− insulin‐resistant mice and Goto‐Kakizaki rats showed decreased autophagy and increased autophagy, respectively." (PMID 38113341, 2024). "Recent guidelines have recommended CGM use in individuals with type 2 diabetes treated with insulin." (PMID 38363342, 2024). "In this study, we investigated the association between insulin secretory capacity and TIR in Japanese patients with type 2 diabetes and impaired insulin secretory capacity." (PMID 38839813, 2024). "The DIAMOND RCT showed that, compared with SMBG, rtCGM resulted in a greater HbA1c reduction (MD −0.3 pp [–3 mmol/mol]) in a type 2 diabetes population treated with multiple daily insulin injections (MDI)." (PMID 38951212, 2024). "Type 2 diabetes (T2D) arises when pancreatic β cells fail to produce sufficient insulin to control blood glucose appropriately." (PMID 39388284, 2024). "They showed that moderate body weight loss (−8 kg) normalized fasting hyperglycemia in patients with poorly controlled type 2 diabetes: by reducing intrahepatic fat (−81%) by a hypocaloric diet, hepatic insulin clearance was improved." (PMID 38791525, 2024).
type 2 diabetes (continued). "Altogether, our findings indicate that bariatric surgery directly improves beta-cell function in patients with insulin-treated type 2 diabetes." (PMID 38589596, 2024). "SGLT2i is a new class of insulin-independent drug for type 2 diabetes, which acts highly selectively on renal proximal tubules to block glucose reabsorption and increase the elimination of excess glucose from the body." (PMID 39247919, 2024). "Numerous previous studies have confirmed the ability of ULP to alleviate the symptoms of type 2 diabetes by reducing blood glucose levels through enhanced insulin sensitivity, as well as boosting superoxide dismutase (SOD) and catalase (CAT) activity." (PMID 39596859, 2024). "Studies reveal CGM's superiority over SMBG, with improved glucose control and reduced variability, applicable to both type 1 and insulin-requiring type 2 diabetes." (PMID 38650779, 2024). "There is likely to be a subgroup of individuals with type 2 diabetes in our insulin-treated group who are also taking a range of oral agents." (PMID 39358593, 2024). "Type 2 diabetes (T2D) constitutes 90% of diabetes cases and begins with reduced insulin sensitivity." (PMID 39484071, 2024). "Around 25% of all patients suffered from type II diabetes preoperatively, with 32% of them requiring insulin therapy for treatment." (PMID 39080285, 2024). "Exogenous insulin is the essential treatment for patients with type 1 diabetes and for patients with insulin-requiring type 2 diabetes, underscoring the critical role of insulin and its analogs in managing the disease." (PMID 39457586, 2024). "Currently, the treatment of type 2 diabetes focuses on oral hypoglycemic drugs and insulin analogues." (PMID 39598478, 2024). "Further, butyrate increases energy expenditure and insulin sensitivity and thus has therapeutic potential in weight control and treatment of type-2 diabetes." (PMID 38248481, 2024). "This reduction in HGP is particularly significant because increased fasting concentrations of HGP and its insensitivity to insulin are characteristic features of type 2 diabetes." (PMID 38920999, 2024). "Specifically, PNX-14’s regulation of insulin expression and secretion from pancreatic beta cells suggests a role in managing glucose homeostasis and treating conditions like type 2 diabetes." (PMID 39398330, 2024). "The first, known as Type 1 diabetes involves the body’s inability to produce insulin and the second is Type 2 diabetes, in which the body can’t efficiently utilize the insulin it produces." (PMID 39024327, 2024). "In this framework, stage 1 represents “insulin resistance”, stage 2 “prediabetes”, stage 3 “type 2 diabetes”, and stage 4 “vascular complications”." (PMID 39200982, 2024). "Mitochondrial dysfunction in adipocytes can adversely impact lipid metabolism, insulin sensitivity, and thermogenesis, contributing to metabolic diseases such as obesity and type 2 diabetes." (PMID 39409659, 2024). "In individuals with T1D or prolonged type 2 diabetes (T2D), unregulated insulin release from subcutaneous depots or the sustained effects of sulfonylureas can result in elevated systemic insulin levels during hypoglycemia." (PMID 38397994, 2024). "Clinical guidelines for type 2 diabetes recommend in most cases metformin in first-line, and insulin only at later stages or in case of severe hyperglycaemia." (PMID 39639300, 2024). "The most effective treatments for type 2 diabetes include lifestyle modifications, oral antihyperglycemic drugs, or insulin therapy." (PMID 39766863, 2024). "The effect of isCGM on BW can vary in those with type 2 diabetes, depending on their insulin regimen." (PMID 37931069, 2024). "Insulin therapy is essential for patients with type 1 diabetes and is also used in advanced type 2 diabetes when other medications fail to maintain adequate glucose control." (PMID 39594624, 2024).